IFNG (interferon gamma)
Diseases named in the same sentence as IFNG in open-access papers (continued):
Sharing a sentence is not in itself a finding about the gene and the disease.
melanoma (continued). "The analysis of gene expression profiles of melanoma patients with checkpoint inhibitor treatment detected IFNγ-related mRNA profiles, which predicted clinical response to PD-1 treatment, underlining the huge clinical benefit of transcriptome sequencing studies." (PMID 35003017, 2021). "Elevated IL2RA, IL2RG, IL7R, and IFNG expression may play a central role in promoting melanoma metastasis via increase in intratumoral regulatory T cell proportion, mainly by activation of the JAK–STAT signaling pathway." (PMID 34159752, 2021). "This hypothesis is supported by experimental evidence that CD8+ T cells produce cytokines like interferon gamma to induce the upregulation of PD-L1 in melanoma." (PMID 34650926, 2021). "Indeed, NKG2D ligands expression induced by DTIC enhanced both perforin/granzyme B-dependent killing of melanoma cells and IFNγ secretion by NK cells." (PMID 34712615, 2021). "Resistance to immunotherapy in melanoma is associated with alterations in the interferon gamma pathway or a lack of MHC-I surface expression." (PMID 34072863, 2021). "Given the previous work that described how oxidative stress and the NRF2 regulator KEAP1 regulated IFNγ-mediated MHCII expression in human melanoma cells, NRF2 regulation and redox dysregulation could explain a possible mechanism for MED16 control of MHCII." (PMID 34747695, 2021). "Additionally, TLR7 activation in melanoma is associated with significant increases in: intratumoral CD8+ T and CD4+ T cells; anti-tumor macrophages, B cells, IFNγ, IFNα/β, and plasmacytoid dendritic cells, and pro-inflammatory cytokines IL6 and IL12." (PMID 32455916, 2020). "Finally, the co-upregulation of IFNγ with six ICPs as well as three ICPRGs was strongly supported by findings in the TCGA cohorts of melanoma, colon, breast, esophageal, stomach, and lung cancer." (PMID 32265897, 2020). "Diminished expression of HLA-ABC (~80% reduction in expression) was driven by two independent B2M-targeting silencing molecules and this significantly reduced the immune recognition of melanoma cells, leading to approximately a 70% reduction in the levels of IFNγ production." (PMID 32312968, 2020). "We also assessed expression of activation-responsive immune genes TNF, IL21, IL10, IL13, and CFS2 in the ICB melanoma dataset, and found that IFNG, TNF, and interleukins IL21 and IL10 seemed to increase upon treatment in responders, even though they were not differentially expressed." (PMID 32471032, 2020). "Specifically, TRIM28 high expression correlated with significant depletion of interferon alpha (IFN-α) and interferon gamma (IFN-γ) response in melanomas, which resulted from significant downregulation of IRF (Interferon Regulatory Factor) transcription factor family members." (PMID 33076560, 2020). "PD-L1 expression is also regulated by interferon gamma signaling in a melanoma cell line." (PMID 32403421, 2020). "In addition to TM-mediated lysis of neuroblastoma and melanoma cells, UniCAR NK-92 cells also secreted high concentrations of IFNγ already after 4 hrs of co-culture with target cells in the presence of TMs." (PMID 32034289, 2020). "Furthermore, SB-3CT led to a decrease in IFNγ-induced PD-L1 surface expression in two melanoma cell lines, SK-MEL-28 and A375, and one lung cancer cell line, A549." (PMID 32988398, 2020). "Indeed, abnormalities in antigen presentation and the interferon gamma (IFNγ) pathways, for example, have been shown to affect the response of melanoma patients to immunotherapy." (PMID 32060274, 2020). "A focused collection of approximately 500 small molecules targeting a broad range of cellular mechanisms was screened, and four active compounds that increased melanoma antigen expression leading to enhanced IFNγ production were identified and their in vitro activity was validated." (PMID 32231230, 2020). "Indeed, they found that treatment of melanoma-patient-derived monocytes with PGE2 leads to the loss of T-cell proliferation and IFNγ production." (PMID 33271839, 2020).
melanoma (continued). "Thus, these 4 compounds enhanced expression of melanoma differentiation antigens resulting in enhanced recognition of melanoma cells leading to T cell activation and enhanced effector function as demonstrated by increase in IFNγ production." (PMID 32231230, 2020). "Together, our data indicate that IDO1 is mainly expressed in tumor endothelial cells of B16-F10 and HCmel12 melanomas and that its expression can be further enhanced by agonistic CD40 mAb therapy and the associated IFNγ expression in the tumor microenvironment." (PMID 32231867, 2020). "Thus, the effect of the 4 compounds on melanoma cells reproduced in an IFNγ secreted ELISA in a 96 well assay format." (PMID 32231230, 2020). "Furthermore, NR2F6 inhibition has been shown to augment the efficacy of ICB in preclinical prostate, melanoma, and colorectal cancer models, as well as increase tumor infiltration by IFNγ-positive T cells." (PMID 32117236, 2020). "Wnt5a secreted by melanoma cells activates β-catenin in DCs which upon nuclear translocation binds the TCF/LEF1 transcription factor responsive elements subsequently inducing IDO expression in an IFNγ-independent manner." (PMID 33072086, 2020). "Moreover, in melanoma and NSCLC patients treated with anti-PD-1 therapies, higher IFNγ protein expression is associated with longer progression-free survival." (PMID 33247183, 2020). "Also, intraperitoneal treatment with chitosan triggers an antitumor immune response in the murine B16 melanoma model through the action of dendritic cells leading to the activation and action of IFNγ secreting NK lymphocytes." (PMID 32410869, 2020). "Moreover, TGFß reduced the recognition of melanoma cells by autologous immune cells resulting in reduced IFNγ production." (PMID 32312968, 2020). "Interestingly, in the presence of IFNγ and TNFα melanoma cells can also upregulate TGFB, IL10, VEGFA, and VEGFC genes, which can further modulate the immunosuppressive phenotype of TAMs." (PMID 32793228, 2020). "Next, we investigated whether FTO knockdown sensitizes melanoma cells to cell death induced by IFNγ." (PMID 31239444, 2019). "Given the impact of TNFα and IFNγ on IL32 expression in melanoma cell lines, we investigated the expression of IL32 in the chemokine-rich melanoma tumor microenvironment using RNA sequencing data from tumor biopsies as part of The Cancer Genome Atlas (TCGA) dataset." (PMID 30953519, 2019). "This hypothesis is supported by results from Zaretsky and colleagues, who showed a resistance to PD-L1 therapy in melanoma based on alterations in the pathways involved with Interferon gamma signaling." (PMID 30709339, 2019). "For instance, in a long time-course study of IFNγ activation of melanoma cells, 4 of the 10 highest regulated miRNAs were ‘star’ strands (miR-424-3p, miR-29b-1-5p, miR-27a-5p and miR23a-5p; current miRbase annotations), that were induced where the partner strands were not45." (PMID 31641696, 2019). "In addition to this, IFNγ was recently described as an upregulator of CTLA-4 in melanoma cells, another long-established immune checkpoint inhibitor." (PMID 31779626, 2019). "Indeed, anti-IFNγ antibody increased melanoma tumor growth in both control and FTO-knockdown cells in mice." (PMID 31239444, 2019). "Next we analyzed the role of FTO in the response of melanoma cells to IFNγ." (PMID 31239444, 2019). "In a mouse melanoma model, mice deficient for MIP-1α/β had increased tumour growth as well as a higher incidence of metastases, also associated with lower local production of IFNγ, TNFα and IL-644." (PMID 30872676, 2019). "Furthermore, we found that overexpression of PD-1 (PDCD1), CXCR4, or SOX10 inhibited IFNγ-induced cell death in FTO-knockdown melanoma cells." (PMID 31239444, 2019). "Moreover, CSPG4-CAR T cells exhibited IFNγ production upon co-culture with human melanoma cells A375M, serving as positive controls." (PMID 31195686, 2019).
melanoma (continued). "Thus, the overall response to melanoma-associated peptides was weak in the majority of patients, with a low percentage of CD8+IFNγ+ cells and a low stimulation index." (PMID 30560089, 2018). "Samples was co-cultured with HLA-matched melanoma cell lines and analyzed for IFNγ production." (PMID 30400822, 2018). "Expression of five well-defined IFNγ targets, the PD-1 ligands PD-L1 and PD-L2, NGFR, antigen-presenting HLA-A, -B, and -C (HLA-ABC), and HLA-DR molecules was examined in a panel of 39 human melanoma cell lines with defined oncogenic driver mutations." (PMID 29977240, 2018). "To investigate the quality and quantity of anti-tumor immune responses in the tumor and their correlation with the success or failure of cancer immunotherapy, we treated IFNγ-venus reporter mice bearing the B16 melanoma with different immunomodulatory antibodies." (PMID 29348598, 2018). "In this study, we examined interferon-γ (IFNγ) responses in a large panel of immune checkpoint inhibitor-naïve melanoma cells with defined genetic drivers; BRAF-mutant (n = 11), NRAS-mutant (n = 10), BRAF/NRAS wild type (n = 10), and GNAQ/GNA11-mutant uveal melanomas (UVMs) (n = 8)." (PMID 29977240, 2018). "Moreover, IFNγ-treated melanoma patients were found to have a worse survival than those who did not receive IFNγ." (PMID 29855346, 2018). "Indeed, high IFNγ expression was shown to be associated with longer progression free survival in non-small cell lung cancer (NSCLC) and melanoma patients treated with anti-PD-1." (PMID 29968076, 2018). "Importantly, nearly 70% of melanoma cells included in this study showed incomplete responses to IFNγ stimulation, indicative of pre-existing resistance to immunotherapy." (PMID 29977240, 2018). "We also examined the influence of melanoma driver oncogenes on IFNγ signaling and our data suggest that UVM have diminished capacity to respond to IFNγ, with lower induced expression of several targets, consistent with the disappointing response of UVM to immunotherapies." (PMID 29977240, 2018). "Furthermore, loss-of-function mutations in the upstream IFNγ-signaling regulators JAK1 and JAK2, concurrent with deletion of the wild type alleles, have been identified in two melanoma patients who failed anti-PD-1 therapy." (PMID 29977240, 2018). "As a-CTLA4-TGFβRII effectively counteracted tumor-infiltrating Tregs in vivo, we examined its ability to increase tumor-reactive IFNγ expression in T cells and inhibit tumor growth in human melanoma tumor-bearing NSG mice that were immune reconstituted with matched HLA A2+ human BM CD34+ cells." (PMID 29467463, 2018). "Indeed, peripheral blood CD8+ T cells from patient Ma-Mel-36 secreted IFNγ in the presence of autologous melanoma cells, as determined by ELISpot assay." (PMID 28561041, 2017). "Our study demonstrates a genetic evolution of IFNγ resistance in different melanoma patient models." (PMID 28561041, 2017). "Furthermore, this experiment supports the notion that the IFNγ response varies significantly among melanomas, and demonstrates tumour-autonomous features." (PMID 26822383, 2016). "In addition, melanoma cells are fragilized in presence of MelanA-specific CTLs or their cytokines IFNγ and TNFα." (PMID 27625650, 2016). "We assessed steady state and IFNγ-induced immunoproteasome expression in melanoma cells." (PMID 26885372, 2016). "In order to establish the functional activity of the adaptive cellular immune system in our cohort of stage IV melanoma patients, we first analysed circulating T cells for their expression of the CD3ζ chain and their capacity to secrete IFNγ in response to stimulation with PMA and ionomycin." (PMID 26176858, 2015). "The selective blockage of PD-L1 may be a potential strategy to improve the therapeutic value of IFNγ-producing ADSCs for melanoma treatment." (PMID 25428727, 2014).
melanoma (continued). "Therefore, in this study we aimed to investigate antitumor activity of φC31/pBt modified murine ADSCs expressing IFNγ and TRAIL individually, or co-expressing Trail/IFNγ in vitro and in mouse subcutaneous or lung metastasis models of melanoma." (PMID 25428727, 2014). "For MTT assay, melanoma cells were incubated in CM from either EGFP-ADSCs or IFNγ-ADSCs." (PMID 25428727, 2014). "Therefore, intravenous injection of IFNγ-ADSC indirectly maintained normal levels of systemic Treg through inhibition of melanoma growth." (PMID 25428727, 2014). "Likewise, the IHC analysis for IFNγ and TUNEL staining showed juxtaposition of IFNγ-ADSCs with melanoma cells." (PMID 25428727, 2014). "Moreover, co-injection of IFNγ-ADSCs with melanoma cells reduced the growth of subcutaneous melanoma tumors." (PMID 25428727, 2014). "Ex-vivo analysis shows that at the peak of the anti-melanoma effector response, melanoma specific Pmel-1 T cells are primed into competent effector cells (shown by surface phenotype, IFNγ secretion and lytic capacity in the periphery) but are unable to mediate tumor regression." (PMID 21731676, 2011). "Moreover we show that in addition to producing the same quantity of cells as the standard procedure using plates, the bag allows an improved expansion of specific CD8+ cells regarding IFNγ production of TIL co-cultured with the autologous melanoma cell line." (PMID 21575188, 2011). "Finally, this higher proportion of CD8+ cells produced correlated with a higher number of CD8+ T cells producing IFNγ when TIL were placed in contact with the autologous melanoma cell line." (PMID 21575188, 2011). "The vaccine (IDD-3) consisted 8 doses of autologous monocyte-derived matured DC generated in serum-free medium with granulocyte macrophage colony stimulating factor (GM-CSF) and interleukin-13 (IL-13), pulsed with lysates of three allogeneic melanoma cell lines, and matured with interferon gamma." (PMID 20875102, 2010). "We therefore performed quantitative ChIP experiments to determine whether binding of CIITA to the new targets is induced by IFNγ in a melanoma cell line exhibiting well documented IFNγ induced CIITA expression." (PMID 18437201, 2008). "We next performed real-time RT-PCR experiments with melanoma cells to determine whether expression of the new target genes is induced by IFNγ." (PMID 18437201, 2008). "The current observation concurs with distinct anti-inflammatory properties of immunoregulatory IFNγ that include modulation of IL-8 secretion as previously noted for other human cell types including monocytes/macrophages, synoviocytes, and melanoma cells." (PMID 18801189, 2008). "Furthermore, we found that IFNγ is a central driver of melanoma sensitivity to NKmK." (PMID 41078003, 2025). "As ADPr-containing p62 bodies are also observed in melanoma cells following IFNγ treatment—and that such ADPr/PARP14 condensation is lost upon RBN treatment—understanding how PARP14-mediated ADP-ribosylation in p62 bodies functions could open new avenues for overcoming immunotherapy resistance." (PMID 40195501, 2025). "How the differentiation status of melanoma cells affects IFNγ responses remains unclear." (PMID 39736644, 2024). "Our results demonstrate that following dedifferentiation the IFNγ response of melanoma cells gets conditioned, leading to a non-additive increase in IFNγ-induced expression of a subset of genes implicated in adaptive immunity, compared to differentiated melanoma cells." (PMID 39736644, 2024). "Furthermore, targeting differentiation could help shape melanoma immunogenicity by modulating the IFNγ signaling of melanoma cells." (PMID 39736644, 2024). "One of our basic hypotheses was that samples with BRCAness respond better to PARPi therapy and that hot tumors with an activated immune milieu respond better to immune checkpoint inhibition, as has been shown, for example, in melanoma for the activated IFNG pathway." (PMID 39669575, 2024).
melanoma (continued). "However, the molecular mechanism governing the effects of IFNγ on the expression of PD-L1 and other immunological genes in dedifferentiated melanoma cells remains unknown." (PMID 39736644, 2024). "Resistance to IFNγ may be widespread, as shown by our results with melanoma lines." (PMID 37803324, 2023). "Thus, inhibition of Ptpn2 by the small-molecule PTP 9 sensitizes melanoma tumors to anti-PD-1 therapy in vivo, at least in part, by restoring the ability to respond to IFNγ, thereby increasing T-cell chemokine expression and recruitment of cytolytic T cells to the tumor microenvironment." (PMID 36968224, 2023). "Enhanced IFNγ gene signature (IFNγ, CD274, LAG3, CXCL9) is associated with higher overall response rates and longer median progression-free survival among metastasized non-small cell lung carcinoma, urothelial cancer or melanoma patients receiving PD-1 inhibitors or anti-PD-L1 antibodies." (PMID 37671945, 2023). "In addition to TLR9 stimulated cytotoxicity of NK cells on B16 melanoma cells, the secretion of inflammatory cytokines as IFNγ and IL-12 was promoted via TLR7/8 activation, which in order aided the NK cells to eliminate the HNSCC cells and B16-F10 melanoma cancer cells." (PMID 37936697, 2023). "Finally, in a study of 54 melanoma patients treated with tumor-infiltrating lymphocyte (TIL) therapy, TIL products showing high expression of memory-associated genes and low expression of granzyme A (GZMA) and interferon gamma (IFN-γ) correlated with response." (PMID 37880715, 2023). "As both IFNγ and IL-12 activate T cells, adoptive transfer of T cells with co-administration of these cytokines may enhance anti-tumour immunity and prevent T cell exhaustion as seen in mouse models of melanoma." (PMID 37455828, 2023). "Moreover, mature DCs are required by EVs to facilitate the differentiation of melanoma-specific effector T lymphocytes, which could produce Interferon gamma (IFN-γ; Tc1) effector lymphocytes in human leukocyte antigen A2 (HLA-A2) transgenic mice (HHD2)." (PMID 34374936, 2022). "And the negative correlation between 6 ICD-related genes (CD8A, PRF1, IFNG, CXCR3, TNF, CD8B) and risk score and the protective function of these 6 genes in SKCM indicates that drugs targeting these genes may be a novel treatment method in melanoma." (PMID 36211436, 2022). "Moreover, the spatial-phenotype-classifier outperformed other, publicly available gene-classifiers that are recognized for capturing lymphocyte activity and location, and for predicting anti-PD1 response in melanoma, such as IFNγ-response, T cell exclusion, and TLS signatures." (PMID 34580291, 2021). "The cell surface expression of PD-L1 was also low in our panel of melanoma cells at baseline and after TNFα induction, although the PD-L1 transcript and protein are both significantly induced, and we have previously shown that this molecule is also highly inducible by IFNγ." (PMID 34073253, 2021). "Finally, elevated NAMPT expression correlates with IFNγ responses and melanoma patient survival." (PMID 33976173, 2021). "We found that SAHA could sensitize the melanoma cells to T-cell killing in IFNγ pretreated group." (PMID 33158915, 2020). "Furthermore, the analysis showed that HLA-DR expression in melanoma cells may be a biomarker for tumors primed with activated T-cells and an appropriate IFNγ response to mediate sensitivity to PD-1/PD-L1 blockade, which is also associated with immune response." (PMID 33392203, 2020). "Analysis of transcriptomes of melanoma patients before and during nivolumab treatment revealed that clinical benefit was associated with reduced expression of SLC3A2, enhanced CD8+ T cell signature and expression of IFNG that was associated with improved overall patient survival." (PMID 32340261, 2020). "Indeed, melanoma cells treated with interferon gamma have markedly suppressed growth." (PMID 31110180, 2019).